LGALS9 (galectin 9)
Diseases named in the same sentence as LGALS9 in open-access papers (continued):
Sharing a sentence is not in itself a finding about the gene and the disease.
tumor (continued). "Considering the effect of Lgals9 in tumor-immune microenvironment and immune infiltration, we performed GSEA, CIBERSORT and LM22 bioinformatic analysis." (PMID 33082168, 2020). "More importantly, the expression of MHC I, CD40 and TAP1 in DCs in GL-261 LGALS9−/− tumor-bearing mouse CSF was significantly higher than that in DCs in GL-261 WT tumor-bearing mouse CSF." (PMID 33093453, 2020). "SUV39H1 overexpression significantly up-regulated the methylation level of HAVCR2 and LGALS9 in tumor tissues." (PMID 32699524, 2020). "We demonstrate improved target knockdown in tumor cell spheroids using two cancer cell lines, consistent with the distribution of chol-siRNA and induced galectin-9 foci throughout the spheroids." (PMID 32286269, 2020). "Galectin-9+TAMs reduced the anti-tumor response of immune cells and promoted tumor growth via T cell exhaustion." (PMID 32508809, 2020). "Using Western blot analysis and confocal microscopy we found very low levels of galectin-9 in human breast tissue cells peripheral to tumor, which were significantly increased in tumor cells." (PMID 31354733, 2019). "We conclude that the Tim-3-galectin-9 pathway is operated by a wide range of human cancer cells and is possibly involved in prevention of anti-tumor immunity." (PMID 31354733, 2019). "Recent evidence clearly demonstrated that some tumor cells (AML in particular) operate the Tim-3-galectin-9 secretory pathway which is capable of disabling cytotoxic lymphoid cells." (PMID 31354733, 2019). "Secondly, TIM-3 and LGALS9 mRNA expression and methylation levels correlated significantly with tumor immune cell infiltration." (PMID 31747929, 2019). "The interaction between TIM-3 and galectin 9 has been shown to induce apoptosis in effector T helper 1 (Th1) cells, consequently resulting in a reduction of autoimmune and anti-tumor immune responses." (PMID 31747929, 2019). "Although only limited tumor types were evaluated, higher galectin-9 expression was reported in a meta-analysis to be related to better prognosis in solid tumors especially in digestive cancers." (PMID 31832021, 2019). "A previous study showed that tumor-infiltrating T-cell-derived IFN-γcontributes to increases in galectin-9 expression in Kupffer cells in the HCC microenvironment." (PMID 29316949, 2018). "Strikingly, although galectin-9 is negatively regulated by miR-22, a well identified tumor suppressor miRNA, galectin-9-overexpression and pre-miR-22 transfection suppressedHCC cell proliferation and migration." (PMID 29316949, 2018). "Strikingly, they showed that blockade of DECTIN-1 or its endogenous ligand Galectin-9, both strongly expressed on infiltrating myeloid cells and tumor, delayed tumor progression and extended mice survival." (PMID 29497419, 2018). "More studies in which galectin-9 expression is correlated with signatures of tumor infiltrating immune cells are required." (PMID 29765332, 2018). "We co-transfected galectin-9-stable cells with pre-miR-22 or empty vectors and found that these cells displayedlower tumor weights and smaller tumorsthan cells transfected with pre-miR-22 or mock alone." (PMID 29316949, 2018). "As the ligand of TIM3, Galectin-9 was not only expressed on tumor cells of invasive front but also on immune cells in the tumor stroma." (PMID 29506555, 2018). "Of all patients, 53 patients (55.79%) and 57 patients (60%) had increased percentages of Galectin-9+ tumour cells and of Foxp3+ lymphocytes, respectively." (PMID 28871094, 2017). "Again, there were significant differences in the percentages of Galectin-9+ tumour cells, Foxp3+ lymphocytes and CD8+ lymphocytes between the paired primary and recurrent NPC." (PMID 28871094, 2017). "The percentages of Galectin-9+ tumour cells and Foxp3+ lymphocytes increased significantly (p < 0.001 and p < 0.001, respectively) in recurrent NPC." (PMID 28871094, 2017).
tumor (continued). "In contrast to primary NPC, more than half of the patients with recurrent NPC had increased percentages of Galectin-9+ tumour cells and of Foxp3+ lymphocytes." (PMID 28871094, 2017). "The means and standard deviations of the percentages of Galectin-9+ tumour cells in primary and recurrent NPC were 29.41 ± 27.87% and 41.14 ± 29.60%, respectively (p = 0.006)." (PMID 28871094, 2017). "In an in vivo study, galectin-9 modulates tumor immunity and suppresses tumor progression as well as directly binds to cell surface glycans and presents direct apoptotic effects." (PMID 28045432, 2017). "When we compared the expression of all immunologic markers in the tumour microenvironment between primary and recurrent NPC, we found significant differences in the mean percentages of Galectin-9+ tumour cells, Foxp3+ lymphocytes and CD8+ lymphocytes." (PMID 28871094, 2017). "In tumor-bearing mice, galectin-9 increased the number of NK cells in the peritoneal exudate, indicating that it plays a potential regulatory role that involves NK cells during tumor progression." (PMID 27028892, 2016). "Immunologically, TIM3 binds to galectin 9 (Gal9) on the surface of antigen-presenting cells (as well as tumour cells) to induce apoptosis of activated T cells." (PMID 27301245, 2016). "Previous studies using tumor-bearing mice showed that administrating galectin-9 increased the numbers of NK cells in the intraperitoneal exudate and enhanced the cytotoxic activity of NK cells." (PMID 27028892, 2016). "Our evaluation of tumor and para-tumor tissue samples that were obtained from 38 patients revealed that galectin-9 was expressed primarily in the cytoplasm on both tumor and normal glandular cells but was not expressed in the nucleus or on cells urfaces." (PMID 27028892, 2016). "Strong correlations were found between galectin-9 single positive cells and galectin-3/9 double positive cells both in the epithelial and in the stromal tumor compartment (R = 0.706, p<0.0001; R = 0.680, p<0.0001, respectively)." (PMID 26066796, 2015). "The tumor cells secrete galectin-9 in the tumor microenvironment that act on TIM-3 to induce apoptosis in the tumor-infiltrating CD8+ T cells." (PMID 26493689, 2015). "Taken together, tumor-derived galectin-9 induces apoptosis in tumor-infiltrating CD8+ T cells and blockade of TIM-3 attenuates the apoptosis and augments anti-tumor activity of infiltrating CD8+ T cells." (PMID 26493689, 2015). "As compared to galectin-3 expression, galectin-9 expression was quite low either in H1299 monolayers or tumor spheres." (PMID 25669973, 2015). "When galectin-9 was expressed by tumor epithelial cells, it was primarily located at the invasive borders." (PMID 26066796, 2015). "The blockade of TIM-3/galectin-9 interaction enhances the therapeutic potential of cyclophosphamide to inhibit tumor growth in mice as well." (PMID 26493689, 2015). "The expression of galectin-9 by tumor cells has generally been correlated with good prognostic markers in different tumor types." (PMID 26066796, 2015). "Addition of recombinant galectin-9 increased apoptosis of the tumor-infiltrating CD8+ T cells when the cells were sorted from tumor-bearing mice on day 28- post tumor inoculation and cultured in vitro." (PMID 26493689, 2015). "The CT26 tumor cells synthesized galectin-9, which was secreted into the tumor tissue of tumor-bearing mice." (PMID 26493689, 2015). "−0.36) while there was a positive correlation between galectin-1 and galectin-9 protein score in the tumor endothelial cells (corr." (PMID 25259711, 2014). "Immunohistochemical assessment of galectin-1 and galectin-9 protein expression showed differences in the localization and distribution within the tumor tissue." (PMID 25259711, 2014). "Previous data suggest that the different galectin-9 isoforms have a diverging role in tumor cells, e.g. they differently affect the adhesion of cells to the ECM and to the endothelium." (PMID 25259711, 2014).
tumor (continued). "Subsequent Pearson correlation analysis of the staining scores showed that there was a significant inverse correlation between the score of galectin-1 and galectin-9 in the tumor cells (corr." (PMID 25259711, 2014). "Regarding carcinomas, we observed increased expression of galectin-9 (P<10−6) in epithelial cells compared to non-tumor pathologies." (PMID 24859692, 2014). "In fact, positive tumor cells were only infrequently observed although some tissues appeared to display a gradient with increasing galectin-9 levels in the tumor cells closer to the stromal tissue." (PMID 25259711, 2014). "Galectin-9 (Gal-9) induces adhesion and aggregation of certain cell types and inhibits the metastasis of tumor cells." (PMID 24339967, 2013). "The Tim-3 ligand galectin-9 was found to prolong the survival of tumor-bearing mice by inducing cytotoxicity in CD8+Tim-3+ T cells, as well as facilitating the maturation of Tim-3+ dendritic cells." (PMID 23526963, 2013). "Galectin-9 is expressed by a variety of tumor cells and play an important role in tumor immunity by regulating the survival, proliferation and migration of both tumor cells themselves and immune cells in the tumor microenvironment." (PMID 23658855, 2010). "Galectin 9 was contained in exosomes from both tumor lines although less abundant in C17 exosomes; an observation that is consistent with the lower amount of galectin 9 in C17 compared to C15 cells." (PMID 17156439, 2006). "Because of the immunomodulatory properties of LMP1 and galectin 9, our observations are expected to have a major impact in the elucidation of host-tumor relationships in NPC patients." (PMID 17156439, 2006). "Furthermore, we found that cGAS, STING, and galectin-9 expression levels were increased in LNP/pNC-treated tumor tissues compared with controls." (PMID 41424839, 2026). "Finally, our results showed that F. nucleatum and its metabolic derivates promote tumor spheroids growth, spheroids-derived cell detachment, epithelial-mesenchymal transition and Galectin-9 upregulation." (PMID 39743544, 2025). "Therefore, the high expression of TIMP1 in tumor epithelial cells promotes LGALS9 expression, which interacts with Treg cells through the GALECTIN pathway, thereby enhancing the immunosuppressive function of Tregs." (PMID 41187171, 2025). "In addition, we observed that both irradiated feeder cells and autologous patient-derived tumor cell lines expressed elevated levels of TIM3 ligand galectin-9, and TIGIT ligands CD112 and CD155." (PMID 41394272, 2025). "Studies have demonstrated that IFNG enhances immune cell infiltration by directly activating CD8+ T cells and modulating other components of the tumor microenvironment, such as CXCLs, MHC-I, and galectin-9 (Gal-9), while counteracting cancer-associated fibroblast (CAF)-mediated immunosuppression." (PMID 41368643, 2025). "The interaction between TIM3 and its ligand, Galectin-9 (LGALS9), triggers T-cell dysfunction characterized by impaired proliferative capacity and cytokine secretion deficiency, ultimately fostering tumor-associated immunosuppression and immune escape mechanisms." (PMID 40838069, 2025). "Taken together, these results validate the relevance of galectin-9 for the migration capacity of naturally occurring DC subsets in a tumor model and illustrate the therapeutic value of intervening galectin-9 signaling axis to restore the migration of tumor-immunocompromised DCs." (PMID 40986321, 2025). "In addition, a statistically significant, weak positive correlation was observed in the different RCC subtypes and kidney specimen with the proliferation marker CXCR4 as well as with the two tumor immune checkpoint molecules HLA-G and LGALS9." (PMID 40699665, 2025). "The interaction between LGALS9 and CD44 may modulate tumor cell functions, as LGALS9 expression positively correlates with NK cell abundance while negatively correlating with neutrophils." (PMID 40747615, 2025).
tumor (continued). "The levels of the myeloid cell-secreted cytokines tumor necrosis factor (TNF), C–C motif chemokine ligand 3 and 4 (CCL3 and CCL4), and monocyte chemoattractant protein- 4 (MCP- 4) increased significantly with treatment, while Galectin- 9, involved in tumor immune evasion, decreased." (PMID 40310569, 2025). "Blocking Galectin-9 led to marked tumor regression and synergized with anti-PD-1 therapy, suggesting that targeting Dectin-1 or its ligand may enhance immunotherapy efficacy in PDA." (PMID 41163402, 2025). "Notably, LGALS9 expression in para- and tumor tissue was predominantly detected in epithelial cells and in tumor cells in particular." (PMID 41323263, 2025). "Meanwhile, high TIM3/Galectin-9 enrichment is related to immunosuppressive tumor microenvironment, severe clinical manifestations, inferior prognosis, and poor response to CHOP-based chemotherapy, and can predict the clinical efficacy of immune checkpoint blockade therapy in DLBCL." (PMID 38369502, 2024). "After loading oxaliplatin and antisense oligonucleotides targeting Galectin-9 into exosomes which were originated from MSCs, they exhibited superior antitumor effects than oxaliplatin and Galectin-9 inhibition alone in mice models with orthotopic tumor." (PMID 39054529, 2024). "However, senescent cells can produce immunomodulatory proteins, such as galectin-9, that will hamper the recruitment of immune cells to the tumor site." (PMID 38195762, 2024). "Therefore, APOC1+ TAMs and CXCL11+ TAMs potentially suppress anti-tumor immunity by inducing T cell dysfunction, exhaustion or even apoptosis through LGALS9 − HAVCR2 pair." (PMID 39232806, 2024). "While, galectin-9 could impact on immune cell numbers on the tumor by inducing apoptosis of T cells." (PMID 38195762, 2024). "The tumorigenicity-related proteins of xenograft tumors detected by immunohistochemistry and fluorescence quantitative RT-PCR assays showed that attenuated ST L forms can reduce the expression of proteins that promote tumor growth and metastasis, such as Lgals9 and MMP9." (PMID 38992056, 2024). "Nevertheless, other studies have demonstrated that tumor-derived EVs can inhibit the proliferation of CD8+ T cells by lowering the levels of IL-2 or inducing CD8+ T cell apoptosis through mechanisms such as Galectin 9 and the FasL-TRAIL pathway." (PMID 39281673, 2024). "Several galectin-9 isoforms are known, resulting from alternative splicing and proteolytic processing of the Gal-9 gene (LGALS9), whereas some of these isoforms are involved in angiogenesis, as their expression is increased in activated and tumor endothelial cells." (PMID 39000016, 2024). "Furthermore, high-dose galectin-9 administration demonstrated anti-tumor effects in CTCL, underscore its potential as a therapeutic target." (PMID 38665428, 2024). "In addition, we also detected the elevated Galectin-9 levels in the tumor tissues from treated mice, possibly due to the accumulation of exogenous Galectin-9." (PMID 38815863, 2024). "Moreover, galectin-1 has been shown to induce tumor immune exclusion by increasing the endothelial expression of checkpoint molecules like PD-L1 as well as galectin-9." (PMID 38990363, 2024). "The tumor endothelium in different cancer types showed elevated galectin-9 expression." (PMID 38990363, 2024). "This may be caused by the impaired immune response of exhausted CD8+TILs induced by high TIM3/Galectin-9 enrichment, thus leading to the formation of the immunosuppressive tumor microenvironment, and the immune escape and proliferation of tumor cells." (PMID 38369502, 2024). "Similarly, the overexpression of another galectin, galectin-9, stimulates the release of galectin-9-expression exosomes from tumor cells, and these exosomes promote angiogenesis." (PMID 38172932, 2024).
tumor (continued). "Interestingly, we observed marked upregulation of a series of immune checkpoints (e.g., CD86, CD80, HAVCR2 and LGALS9) in most tumor infiltrating myeloid cells, and a unique pattern in TAMs (e.g., NECTIN2, TNFRSF14, CD276 and TNFRSF9)." (PMID 38414027, 2024). "It has been reported that M2 macrophages highly expressed Galectin-9, and Galectin-9 could also polarize macrophages toward the M2 phenotype, further inhibiting the anti-tumor function of T lymphocytes through TIM3/Galectin-9 pathway." (PMID 38369502, 2024). "Our study further reveals that ATXN3 exerts its tumor-suppressive functions by safeguarding Galectin-9, a carbohydrate-binding protein known for inducing apoptosis and inhibiting the proliferation of human cancer cells, from ubiquitination-mediated proteasomal degradation." (PMID 38815863, 2024). "The significant statistical interaction between TGFB2 and the nine marker genes suggests that TGFB2 is a negative prognostic indicator at low levels of the IFN-I activated genes and TAM marker expression, including the immune checkpoint LGALS9 (upregulated 16.5-fold in tumor tissue; p < 0.0001)." (PMID 39457004, 2024). "Similarly, TIM-3, which is highly expressed in tumor-infiltrating lymphocytes, suppresses anti-tumor immunity through its interaction with Galectin 9 in various cancers." (PMID 39769271, 2024). "Regarding TAMs, a study indicated that Dectin-1 expression is increased on TAMs in the tumor microenvironment of PDAC, promoting tumor progression by inducing the generation of tolerant macrophages and inhibiting adaptive immunity through binding with galectin-9." (PMID 39590166, 2024). "Furthermore, in the tumor tissue, the upregulated ligand-receptor pairs mostly existed in the macrophage-macrophage communication including Thbs1-, Spp1-, Lgals9-, and Csf-related pairs, which were highly related to immunity suppression." (PMID 36718369, 2023). "Furthermore, galectin-9 can inhibit melanoma cancer metastasis by triggering the aggregation of cancer cells, which impairs cell detachment and escape from the primary tumor." (PMID 36873388, 2023). "In the indirect mechanism, galectin-9 controls tumor immunity against HCC." (PMID 37047155, 2023). "In addition to CEACAM-1, three other ligands are expressed on tumor cells, galectin-9, high mobility group box 1 (HMGB1), and phosphatidylserine (PtdSer)." (PMID 37055849, 2023). "The results showed that blockade of galectin-9 significantly attenuated CD8+ T-cell inhibition mediated by tumor-associated mast cells, which indicated an immune-suppressive effect of tumor-associated mast cells in tumor immunity." (PMID 37042867, 2023). "The immune‐related gene LGALS9 can also inhibit tumor cell proliferation by inducing apoptosis." (PMID 38125769, 2023). "Furthermore, LGALS9 secreted from TAM facilitated tumor migration and maintenance of extracellular matrix homeostasis by binding to DAG1 on GSCL and Class-G cells." (PMID 37964983, 2023). "In addition, we found that tumor-associated CD8+ T cells expressed a higher level of T-cell immunoglobulin domain and mucin domain-3 (TIM-3, the receptor of galectin-9) than non-tumor CD8+ T cells." (PMID 37042867, 2023). "Noticeably, several immune checkpoints were significantly overexpressed in the S-AOIs as compared to E-AOIs, such as the T-cell-specific inhibitory receptor HAVCR2 and its corresponding tumor ligand LGALS9, or the inhibitory CD86 that interacts with CTLA4 on T-cells." (PMID 37460925, 2023). "Galectin-9 is highly expressed in hepatocellular carcinoma cell lines and, as one of the ligands of Tim-3, can bind to Tim-3 on Treg cells, thus promoting Treg cells activation and participating in the immune escape of tumor cells." (PMID 37055849, 2023). "Galectin-9 (Gal-9), the ligand of Tim-3, is expressed mainly in tumor cells." (PMID 37072770, 2023). "Galectin-9 expression in tumour cells was found to be induced by extracellular cytokine signaling." (PMID 36817445, 2023).